NXF2 (nuclear RNA export factor 2)
Description:
Involved in the export of mRNA from the nucleus to the cytoplasm.
Synonyms: CT39; TAPL-2
Tractability: No criterion of Open Targets' tractability assessment is met for any kind of drug.
Gene: Protein-coding gene on chromosome X (102,247,167 to 102,326,722, forward strand). Ensembl gene ENSG00000269405.
Subcellular location: Nucleus, nucleoplasm; Cytoplasm
Pathways (Reactome):
Metabolism of RNA: Transport of Mature mRNA derived from an Intron-Containing Transcript
Gene Ontology:
Molecular function: protein binding; RNA binding; nucleic acid binding
Biological process: mRNA export from nucleus; poly(A)+ mRNA export from nucleus; RNA transport; mRNA transport
Cellular component: nuclear RNA export factor complex; cytoplasm; cytosol; nucleoplasm; nucleus
Homologues: Orthologues: rat Nxf7 (56% identical), mouse Nxf7 (54% identical), rat Nxf2 (53% identical), mouse Nxf2 (52% identical), zebrafish nxf1b (46% identical), tropical clawed frog nxf1 (45% identical), zebrafish nxf1a (39% identical), Caenorhabditis elegans nxf-1 (25% identical), Caenorhabditis elegans nxf-2 (17% identical), Drosophila melanogaster nxf4 (13% identical). Paralogues in human: NXF2B (100% identical), NXF1 (58% identical), NXF3 (46% identical).
Diseases named in the same sentence as NXF2 in open-access papers:
NXF2 is named in the same sentence as 5 diseases in open-access papers, as found by Europe PMC text mining. Sharing a sentence is not in itself a finding about the gene and the disease. The quoted sentences say what the papers report.
breast carcinoma (2 papers, 2011 to 2013). "In addition, the three other CT antigens –GAGE, SAGE1 and Nuclear RNA export factor 2 (NXF2), were infrequently or rarely expressed, only in 3.5%, 2.2% and 1.8% of the breast cancer patients, respectively." (PMID 23451156, 2013). "We found different CT antigens to be significantly different in their CT expression rate in breast cancer, and GAGE, NXF2 and SAGE1 were rarely expressed even in the ER-negative group." (PMID 21437249, 2011).
male infertility (2 papers, 2018 to 2025). The inability of the male to effect fertilization of an ovum after a specified period of unprotected intercourse. "NXF2-deficient mice exhibit defects in spermatogonia proliferation as well as defective spermatid formation, resulting in male infertility." (PMID 29513658, 2018). "However, as no men harboring potentially deleterious variants in NXF2 have been identified yet, it remains to be seen whether loss of NXF2 will also results in human male infertility." (PMID 40624043, 2025).
acute leukemia (1 paper, 2021). A clonal (malignant) hematopoietic disorder with an acute onset, affecting the bone marrow and the peripheral blood. "Bone marrow samples derived from primary acute leukemia patients (n=8) also showed upregulation of NXF2 mRNA expression following decitabine treatment, and NFX2 was also upregulated in all AML or MDS patients (n=9) treated with decitabine." (PMID 33718188, 2021). "Treatment of multiple human acute leukemia cell lines (Kasumi-1, U937, NB4, THP-1, Jurkat, and Molt-4) with decitabine activated the expression of the CTA nuclear RNA export factor 2 (NXF2)." (PMID 33718188, 2021).
female sterility (1 paper, 2019). "Both Nxf2 and Nxt1 were previously identified in screens for piRNA-guided silencing in somatic and germline cells, and their depletion resulted in female sterility." (PMID 31219034, 2019).
cancer (3 papers, 2011 to 2020). A tumor composed of atypical neoplastic, often pleomorphic cells that invade other tissues. "Other cancer/testis antigens such as PAGE1 and NXF2 (cancer/testis antigen 39) were also found associated with this gene cluster." (PMID 33303959, 2020). "In comparison, GAGE, SAGE1 and NXF2 were only expressed in 3–5% of ER-negative and 0–2% of ER-positive cancers." (PMID 21437249, 2011).